NOL9 (nucleolar protein 9)
Description:
Polynucleotide kinase that can phosphorylate the 5'-hydroxyl groups of single-stranded and double-stranded RNA and DNA substrates. Involved in rRNA processing and its kinase activity is required for the processing of the 32S precursor into 5.8S and 28S rRNAs, more specifically for the generation of the major 5.8S(S) form. Required for the efficient pre-rRNA processing of internal transcribed spacer 2 (ITS2). Associates with LAS1L to form an ITS2 pre-rRNA endonuclease-kinase complex and is responsible for the transport of this complex into the nucleolus.
Synonyms: FLJ23323; NET6; Grc3
Tractability: PROTAC: UniProt records ubiquitination sites on it; ubiquitination databases record sites on it; its protein half-life has been measured.
Gene: Protein-coding gene on chromosome 1 (6,521,347 to 6,554,536, reverse strand). Ensembl gene ENSG00000162408.
Subcellular location: Nucleus; Nucleus, nucleolus
Subcellular location (Human Protein Atlas): Nucleoli; Intermediate filaments
Pathways (Reactome):
Metabolism of RNA: Major pathway of rRNA processing in the nucleolus and cytosol
Gene Ontology:
Molecular function: ATP-dependent polydeoxyribonucleotide 5'-hydroxyl-kinase activity; ATP-dependent polyribonucleotide 5'-hydroxyl-kinase activity; protein binding; ATP binding; polynucleotide 5'-hydroxyl-kinase activity; ATP-dependent polynucleotide 5'-hydroxyl-kinase activity
Biological process: maturation of 5.8S rRNA; cleavage in ITS2 between 5.8S rRNA and LSU-rRNA of tricistronic rRNA transcript (SSU-rRNA, 5.8S rRNA, LSU-rRNA); RNA processing
Cellular component: membrane; nucleolus; nucleus; rixosome complex; nucleoplasm
Genetic constraint (gnomAD): Loss-of-function variants: 28 observed, 61.15 expected, observed/expected ratio (o/e) 0.46, 90% interval 0.34 to 0.63. The upper end of that interval is the gene's LOEUF score, 0.63, which puts it in group 2 of 6, group 1 being the genes least tolerant of losing a copy. Missense variants: 747 observed, 836.29 expected, observed/expected ratio (o/e) 0.89, 90% interval 0.84 to 0.95. Synonymous variants: 338 observed, 321.55 expected, observed/expected ratio (o/e) 1.05, 90% interval 0.96 to 1.15.
Homologues: Orthologues: chimpanzee NOL9 (99% identical), macaque NOL9 (97% identical), dog NOL9 (79% identical), pig NOL9 (77% identical), rabbit NOL9 (73% identical), guinea pig NOL9 (72% identical), rat Nol9 (61% identical), mouse Nol9 (60% identical), tropical clawed frog nol9 (42% identical), zebrafish nol9 (35% identical), Drosophila melanogaster CG8414 (21% identical), Caenorhabditis elegans nol-9 (18% identical). Paralogues in human: CLP1 (13% identical).
Diseases named in the same sentence as NOL9 in open-access papers:
NOL9 is named in the same sentence as 6 diseases in open-access papers, as found by Europe PMC text mining. Sharing a sentence is not in itself a finding about the gene and the disease. The quoted sentences say what the papers report.
acute myeloid leukemia (1 paper, 2025). Acute myeloid leukemia (AML) is a group of neoplasms arising from precursor cells committed to the myeloid cell-line differentiation. "NOL9’s multifaceted involvement in cancer biology is underscored by its aberrant expression patterns in malignancies such as triple-negative breast cancer and acute myeloid leukemia." (PMID 39955289, 2025).
hepatocellular carcinoma (1 paper, 2025). A malignant tumor that arises from hepatocytes. "In this study, we examined the role of RiboSis in the progression from hepatitis B virus (HBV) infection to HBV-related hepatocellular carcinoma (HCC), focusing specifically on nucleolar protein 9 (NOL9) and its influence on HCC pathogenesis and therapeutic response." (PMID 39955289, 2025).
schizophrenia (1 paper, 2016). A major psychotic disorder characterized by abnormalities in the perception or expression of reality. "In BA 44 there were lower levels of SNCA (p = 0.03) and NOL9 (p = 0.03), and a strong trend to lower levels of PPIA (p = 0.06), mRNA in subjects with schizophrenia." (PMID 27206773, 2016). "To address this issue we measured levels of mRNA for six potential reference genes (GAPDH, PPIA, SNCA, NOL9, TFB1M and SKP1) in three cortical regions (Brodmann’s areas (BA) 8, 9 and 44) from 30 subjects with schizophrenia and 30 age and sex matched controls." (PMID 27206773, 2016). "By contrast we are aware of no studies reporting change in levels of SNCA or NOL9 mRNA in the cortex of subjects with schizophrenia." (PMID 27206773, 2016).
cancer (2 papers, 2018 to 2025). A tumor composed of atypical neoplastic, often pleomorphic cells that invade other tissues. "Moreover, nonsense mutations were detected in GRHL2, GRIN1, NOL9 and TTC21B, however only GRHL2 and GRIN1 were previously shown to be involved in cancer." (PMID 29854292, 2018). "NOL9, as a key participant in pre-rRNA cleavage and 28S rRNA maturation, is essential for the cell cycle, and its dysregulation may lead to genomic instability, impaired proliferation, and ultimately, disease states such as cancer." (PMID 39955289, 2025).
tumor (1 paper, 2025). "Previously, we found that elevated NOL9 expression is linked to tumor progression and poor prognosis in HCC, highlighting its potential as a prognostic marker and therapeutic target." (PMID 39955289, 2025). "Our previous histochemical staining of clinical specimens found that NOL9 was upregulated in tumor tissues of HCC patients with sorafenib resistance." (PMID 39955289, 2025). "In vivo studies confirmed that NOL9 depletion reduced tumor growth." (PMID 39955289, 2025). "In this study, we aim to clarify NOL9’s role in HCC cell proliferation and tumor development, emphasizing the epigenetic mechanisms driving its aberrant expression." (PMID 39955289, 2025). "Our findings showed that NOL9 was significantly upregulated in HCC tissues, correlating with larger tumor sizes and more advanced pathological grades." (PMID 39955289, 2025). "In conclusion, our study demonstrates that NOL9, which is upregulated in HCC tissues, drives tumor progression and influences resistance to sorafenib." (PMID 39955289, 2025).
NOL9 also shares sentences with these, for which no sentence is quoted: triple-negative breast carcinoma (1 paper).